HUNK (hormonally up-regulated Neu-associated kinase)
Diseases named in the same sentence as HUNK in open-access papers:
HUNK is named in the same sentence as 15 diseases in open-access papers, as found by Europe PMC text mining. Sharing a sentence is not in itself a finding about the gene and the disease. The quoted sentences say what the papers report.
breast carcinoma (9 papers, 2012 to 2022). "In particular, knocking down HUNK in HER2/neu+ breast cancer models causes impaired mammary tumorigenesis, even in resistant models." (PMID 36551828, 2022). "Hormonally upregulated neu-associated kinase (HUNK) is an approximately ~80 kDa serine/threonine (S/T) protein kinase that has been reported to be expressed in about 50% of breast carcinomas." (PMID 36551828, 2022). "Normal mammary gland development in mice is associated with HUNK activity, and breast cancer progression and metastasis has also been attributed to HUNK." (PMID 36551828, 2022). "HUNK is upregulated in HER2+ breast cancer and high HUNK expression is associated with poor prognosis." (PMID 36551828, 2022). "Experimental evidence to date mainly indicates that HUNK over-activity or over-expression is associated with poorer outcomes for breast cancer." (PMID 36551828, 2022). "Although we demonstrated the tumor suppression role of ITM2A in human breast cancer patients, more future studies are needed to underline the roles of the HUNK/ITM2A axis." (PMID 31438969, 2019). "We also linked the protein phosphorylation modification of ITM2A by HUNK, a serine/threonine kinase significantly connected with human breast cancer overall survival and HER2-induced mammary tumorigenesis." (PMID 31438969, 2019). "Hormonally Up-regulated Neu-associated Kinase (HUNK) is a Serine (Ser)/Threonine (Thr) kinase that is highly expressed in HER2+ breast cancers and HER2/neu+ transformed breast or mammary tumor cell lines." (PMID 30542510, 2018). "HUNK is a protein kinase that is implicated in HER2-positive (HER2+) breast cancer progression and resistance to HER2 inhibitors." (PMID 30542510, 2018). "Prior studies show that HUNK is overexpressed in HER2/neu+ breast or mammary tumor cell lines and that HUNK-deficient breast and mammary tumor cells have reduced viability." (PMID 30542510, 2018). "Prior studies show a clear pathogenic role for HUNK in breast cancer." (PMID 36551828, 2022). "HUNK was involved in transferase activity, transfer phosphorus-containing groups, and protein tyrosine kinase activity, and was thought to play a role in breast cancer metastasis." (PMID 36685960, 2022). "HUNK’s role in metastasis is limited to studies predominantly in the basal breast cancer subtype and there is a general consensus that HUNK promotes metastasis." (PMID 36551828, 2022). "Prior studies show that high HUNK expressions correlates with HER2 amplification in breast cancer and poor prognosis." (PMID 36551828, 2022). "In HER2+ breast cancer cell lines and mammary tumors, evidence suggests that HUNK regulates both autophagy and apoptosis making it a critical survival protein in HER2+ breast cancer." (PMID 36551828, 2022). "In breast cancer, there is less than a 2% mutation frequency for mTOR (1.9%), AMPK (1.8%), and HUNK (1.3%)." (PMID 36551828, 2022). "This review article will provide an analysis of what is currently known about HUNK substrates and signaling, and will address new findings about HUNK alterations in cancer, with focus on breast cancer." (PMID 36551828, 2022). "Since the protein was discovered, there has been mounting evidence of HUNK’s role as a pro-tumorigenic protein, particularly in breast cancer." (PMID 36551828, 2022). "HUNK is upregulated in response to oncogenic HER2/neu and Akt, and there is strong evidence that HUNK is critical for the survival of breast cancer cells." (PMID 36551828, 2022). "Here, the incidence and consequence of HUNK alterations in breast cancer is reviewed using data mined from the online database cBioPortal and considered in relation to prior research studies." (PMID 36551828, 2022). "Further evidence shows that inhibiting HUNK using a variety of breast cancer models, including those that are resistant, inhibits tumorigenesis and metastasis." (PMID 36551828, 2022).
breast carcinoma (continued). "We found that through the phosphorylation of EGFR at T654, HUNK significantly increased metastatic phenotypes in breast cancer cells and mammary tumor metastasis in vivo." (PMID 31597954, 2020). "Additional studies show that HUNK plays a role in breast cancer metastasis, likely in the triple-negative subtype." (PMID 32676513, 2020). "To investigate the effects of pharmacological inhibition of HUNK on breast cancer metastasis in vivo, we orthotopically implanted 4T1 cells into the abdominal mammary gland of BALB/c mice." (PMID 31597954, 2020). "Interesting, HUNK is reported to participate in metastasis through mechanisms that are independent from its activity in the HER2+ breast cancer subtype." (PMID 32676513, 2020). "Here, we discuss HUNK’s role in metastasis by reviewing past publications and discussing our current findings, including kinase dependent mechanisms for HUNK in driving breast cancer metastasis." (PMID 32676513, 2020). "Our study significantly differed from either of the prior studies because we identified a direct substrate of HUNK that provided a mechanism for the metastatic behavior of the mammary tumor and breast cancer cell lines we tested." (PMID 32676513, 2020). "Separate from the two prior studies, our study showed that HUNK phosphorylates the epidermal growth factor receptor (EGFR) at threonine (T) 654 to regulate breast cancer metastasis, providing a discrete HUNK-kinase dependent mechanism for this process." (PMID 32676513, 2020). "In particular, a role for HUNK in breast cancer is evident, given that this kinase was originally isolated from the mouse mammary gland." (PMID 32676513, 2020). "Our group recently provided evidence that supports the conclusion that HUNK is a metastasis promoting factor by showing that HUNK regulates breast cancer metastasis through phosphorylation of EGFR." (PMID 32676513, 2020). "Most importantly, this is the first study to highlight EGFR T654 phosphorylation as a mechanism for breast cancer metastasis, and the first to show that pharmacological inhibition of HUNK impairs breast cancer metastasis." (PMID 31597954, 2020). "Here, we summarize our findings and discuss their implications toward pharmacological targeting of HUNK in breast cancer." (PMID 32676513, 2020). "With these conflicting views on HUNK’s role in breast cancer metastasis, further investigation is needed." (PMID 31597954, 2020). "Prior studies show HUNK expression is regulated by Human Epidermal Growth Factor Receptor 2 (HER2) oncogene activation in breast cancer and that HUNK expression is important for tumor cell survival in the HER2-positive (HER2+) subtype of breast cancer." (PMID 32676513, 2020). "We engineered BT20 and MDA-MB-468 (human EGFR+ breast cancer cell lines) cells with control shRNA (targeted to firefly luciferase) or shRNA targeted to HUNK (HUNK shRNA1 and shRNA2)." (PMID 31597954, 2020). "Taken all together, our results suggest that pharmacological inhibition of HUNK impairs the phosphorylation of EGFR at T654 in primary mammary tumors and consequently, impairs metastasis." (PMID 31597954, 2020). "HUNK has been shown to be highly expressed in HER2 positive breast cancer cell lines and to supporte the survival of HER2/neu-positive tumor cells." (PMID 31438969, 2019). "Our findings show that STU reduces cell viability of HER2/neu+ breast and mammary tumor cells as well as HER2-inhibitor (trastuzumab and lapatinib) resistant HER2+ human breast cancer cells, which are dependent on HUNK as a pro-survival signaling molecule." (PMID 30542510, 2018). "Recent reports have also shown that using shRNA to impair HUNK expression suppresses in vivo tumor growth of orthotopic mammary tumors generated from HER2+ breast cancer cells that are resistant to HER2 inhibitors." (PMID 30542510, 2018).
breast carcinoma (continued). "Though prior studies suggest there is therapeutic potential for targeting HUNK in HER2+ breast cancer, pharmacological agents that target HUNK are yet to be identified." (PMID 30542510, 2018). "Since we show that STU inhibits HUNK kinase activity by biochemical assay, as a whole, these findings support previous studies that indicate HUNK inhibition is likely beneficial in the treatment of HER2+ resistant breast cancer." (PMID 30542510, 2018). "Preclinical studies have indicated HUNK’s potential as a novel therapeutic target in HER2+ breast cancer." (PMID 30542510, 2018). "Our collective results, past and present, indicate that HUNK inhibition is effective in HER2+ breast cancer models and application of STU acts synergistically with the HER2 inhibitor lapatinib in JIMT-1 cells, a cell line inherently resistant to lapatinib." (PMID 30542510, 2018). "HUNK has been shown to promote survival in HER2+ breast cancer cells, and to promote mammary tumorigenesis in vivo." (PMID 30542510, 2018). "SMF (MMTV-neu) murine derived mammary tumor cells, which have high HUNK expression levels, were treated with increasing doses of STU, UCN-01, or lestaurtinib." (PMID 30542510, 2018). "Taken together, these findings implicate HUNK targeting as an effective combination that can be paired with JNK inhibition in HER2-inhibitor resistant breast cancers." (PMID 27045589, 2016). "We also investigate potential combination strategies to bolster the effects of JNK inhibition and find that co-targeting of JNK and the protein kinase HUNK can prohibit tumor growth of resistant HER2-positive mammary tumors in vivo." (PMID 27045589, 2016). "Experimental studies indicate a relationship between HUNK and breast cancer progression." (PMID 31597954, 2020). "al. reported that HUNK suppresses metastasis in basal type breast cancers." (PMID 32676513, 2020). "However, no studies have been conducted to examine a relationship between EGFR and HUNK in breast cancer metastasis." (PMID 31597954, 2020). "Thus, this is the first study to show that the pharmacological inhibition of HUNK reduces metastatic potential of breast cancer cells." (PMID 31597954, 2020). "HUNK has been found to play a role in breast cancer metastasis." (PMID 32676513, 2020). "Identification of bona fide substrates could give more insight into HUNK’s intracellular functions, particularly in breast cancer." (PMID 31597954, 2020). "Based on these findings, we concluded that HUNK promotes breast cancer metastasis." (PMID 32676513, 2020). "al. reported that HUNK promotes mammary tumor metastasis using a MMTV-myc mammary tumor model." (PMID 32676513, 2020). "Moreover, we found that ITM2A was phosphorylated at T35 by HUNK, a serine/threonine kinase significantly correlated with human breast cancer overall survival and HER2-induced mammary tumorigenesis." (PMID 31438969, 2019). "HUNK was reported to promote autophagy and breast cancer survival in response to lapatinib." (PMID 31438969, 2019). "According to our findings, which showed a significant prognostic effect of ITM2A in HER2-E subtype breast cancer patients, it presents huge possibility that HUNK could phosphorylate ITM2A." (PMID 31438969, 2019). "Collectively, our studies support the therapeutic potential of targeting HUNK in HER2+ breast cancer cells and indicate that targeting HUNK in combination with HER2 inhibition may be a possible option for HER2+ resistant breast cancers." (PMID 30542510, 2018). "Because breast cancer stem cells are implicated in HER2 inhibitor resistance, identifying targets like HUNK that potentially regulate self-renewal capability may aid in preventing acquired resistance." (PMID 30542510, 2018). "We also evaluated EGFR and AKT signaling, as HUNK has been previously implicated in both of these signaling pathways and the activity of those proteins are often deregulated in HER2-inhibitor resistant breast cancers." (PMID 27045589, 2016).
breast carcinoma (continued). "However, another study provided evidence that HUNK suppresses basal breast cancer metastasis." (PMID 31597954, 2020). "Consequently, future studies will be required to address whether phosphorylation of Rubicon by HUNK supports the development of resistance in breast cancer." (PMID 31752345, 2019). "Taken together, our results indicate HUNK inhibition using a pharmacological inhibitor may be a novel therapeutic approach for HER2+ breast cancer and that targeting HUNK in conjunction with HER2 inhibition will be beneficial for the treatment of refractory HER2+ breast cancer." (PMID 30542510, 2018). "Experimental studies showing that HUNK promotes tumor progression of HER2/neu+ breast cancer and metastasis of basal-type breast cancer confirm the gene expression analyses." (PMID 36551828, 2022). "This group used the human basal-type breast cancer cell lines, MDA MB 468 and MDA MB 231 cells, to show that exogenous expression of HUNK in these cell lines suppresses transwell invasion as well as in vivo metastasis." (PMID 32676513, 2020). "Altogether, we have shown that HUNK promotes metastasis by phosphorylating EGFR, resulting in downstream signaling events that drive metastatic behavior of breast cancer cells." (PMID 31597954, 2020). "Our findings further suggest that inhibiting HUNK with staurosporine has a strong effect on suppressing cell viability of HER2/neu mammary and breast cancer cells, which express high levels of HUNK protein and are dependent on HUNK for survival." (PMID 30542510, 2018). "Previous studies indicate that HUNK knockdown in trastuzumab/lapatinib-resistant, HER2+ JIMT-1 cells shows decreased orthotopic mammary tumor growth." (PMID 30542510, 2018). "To explore other methods of targeting autophagy we next turned to evaluate a protein kinase called HUNK, which we recently described as an activator of autophagy in HER2+ breast cancer cells, potentially contributing to trastuzumab and lapatinib resistance." (PMID 27045589, 2016). "This point is important to note because the fundamental mechanism for HUNK in HER2+ breast cancer is different from metastasis since tumor growth is not affected by HUNK targeting in metastatic models." (PMID 31597954, 2020). "To investigate a role for HUNK regulation of EGFR in breast cancer, we used shRNA to target HUNK in human breast cancer cell lines that have high EGFR expression, without altering PKC activity." (PMID 31597954, 2020). "To evaluate whether co-targeting of JNK and HUNK had an added effect on breast cancer cell death of JIMT-1 cells we next treated control and HUNK knockdown cells with JNK inhibitor and evaluated the cells for Caspase-3 activity." (PMID 27045589, 2016). "While a prior publication demonstrates that pharmacological targeting of HUNK can impede tumor growth, those studies were performed in a resistant HER2-positive (HER2+) breast cancer cell model and not a metastatic breast cancer model." (PMID 31597954, 2020).
colon cancers (1 paper, 2020). "Hormonally Up-regulated Neu-associated Kinase (HUNK) is a serine/threonine kinase that is a member of the AMP-activated protein kinase (AMPK) family, and was reported to be up-regulated in aggressive subsets of human cancers including breast, ovarian, and colon cancers." (PMID 31597954, 2020).
leiomyosarcoma (1 paper, 2025). An uncommon, aggressive malignant smooth muscle neoplasm, usually occurring in post-menopausal women. "The overexpressed kinases in osteosarcoma, liposarcoma, and leiomyosarcoma are mainly serine/threonine kinases (BUB1, CKD4, HUNK, LKKK1, NEK2, PBK, PLK1, and PLK4), whereas TTK has a dual role (Tyrosine and serine/threonine kinase) and only MELK presents tyrosine phosphorylation activity." (PMID 40723917, 2025).
triple-negative breast carcinoma (1 paper, 2025). An invasive breast carcinoma which is negative for expression of estrogen receptor (ER), progesterone receptor (PR), and human epidermal growth factor receptor 2 (HER2). "HUNK expression is also associated with the distant metastasis-free survival and OS of patients with triple-negative breast cancer." (PMID 41487817, 2025). "HUNK is implicated in tumorigenesis, metastasis, and invasion via epidermal growth factor receptor activation in HER2-positive and triple-negative breast cancers." (PMID 41487817, 2025).
tumor (10 papers, 2012 to 2024). "Tumor cells isolated from MMTV-c-myc;Hunk−/− mice that express wildtype HUNK or a kinase-deficient form of HUNK showed that HUNK kinase activity is required for tumor cell migration, invasion, and metastasis." (PMID 36551828, 2022). "Furthermore, a previous study demonstrated that HUNK expression becomes significantly upregulated from the earliest stages of tumor initiation following Apc loss, indicating this gene is probably a Wnt signaling target gene." (PMID 38304289, 2023). "Very few substrates and functions are identified for HUNK but to date the majority of downstream signaling consequences clearly indicate a pro-tumor, cancer supportive function for this kinase." (PMID 36551828, 2022). "In the HER2+ subtype, HUNK regulates the cell survival pathways, autophagy and apoptosis, to promote tumor cell survival and therapeutic resistance to HER2 inhibitors." (PMID 32676513, 2020). "Previous studies have shown that expression of the K91M kinase-dead mutant of HUNK significantly impairs tumor growth in an MMTV-neu model." (PMID 30542510, 2018). "This outlines a paracrine signaling loop between tumor cells and TAMs, governed by HUNK and mediated through IL-4/IL-4 receptor interactions, and targeting HUNK could be a TAM-altering strategy." (PMID 39409110, 2024). "Long-term HUNK overexpression in the breast does not lead to spontaneous tumor formation." (PMID 36551828, 2022).
cancer (5 papers, 2012 to 2023). A tumor composed of atypical neoplastic, often pleomorphic cells that invade other tissues. "Hormonally Upregulated Neu-associated Kinase (HUNK), a serine-threonine protein kinase regulates cancer cell survival, proliferation and metastasis." (PMID 37193711, 2023). "HUNK plays an important role in cancer cell proliferation, survival, as well as metastasis, and is an emerging therapeutic target for cancer treatments." (PMID 37193711, 2023). "This study provides the underlying mechanism for HUNK inhibited EMT and metastasis, thus pave a way for targeting cancer metastasis." (PMID 37193711, 2023). "In consistent with our study, it has been demonstrated that HUNK suppresses cancer metastasis by competitively binding to CFL-1 and protecting dephosphorylation of CFL-1 by PP2A." (PMID 37193711, 2023). "The conflicting conclusions for HUNK-mediated cancer metastasis are probably resulted from option of the signaling pathway, cellular-context dependence, or cell-type specificity in either cell proliferation or metastasis." (PMID 37193711, 2023). "HUNK is a serine/threonine kinase, and plays an important role in many cancer types, including CRC." (PMID 37193711, 2023). "The previous studies showed that HUNK regulates cancer metastasis via different mechanisms." (PMID 37193711, 2023). "In other cancer cells, whether HUNK is involved in metastasis and the potential mechanism are unclear." (PMID 37193711, 2023). "First, a pan-cancer search of alteration frequency focused on two major cancer kinases, mTOR and AMPK, was conducted and compared to HUNK." (PMID 36551828, 2022).
HUNK also shares sentences with these, for which no sentence is quoted: atherosclerosis (1 paper); breast tumors (1); colorectal cancer (1); hematological malignancies (1); liposarcoma (1); metastatic colorectal cancer (1); osteosarcoma (1); prolactinoma (1); Williams syndrome (1).